TNF (tumor necrosis factor)
Diseases named in the same sentence as TNF in open-access papers (continued):
Sharing a sentence is not in itself a finding about the gene and the disease.
inflammation (continued). "As expected, β-glucan treatment remarkably reduced neutrophil numbers in BALF and lung tissue, M. pneumoniae burden and LDH levels in BALF, and the levels of proinflammatory cytokines (IL-1β, IL-6, and TNF-α), which led to the remission of lung inflammation." (PMID 39499730, 2024). "The observation that TNF-α disrupts ENaC activity considerably at concentrations seen in Th1-mediated airway inflammation suggests its potential role in the pathogenesis of these conditions." (PMID 39052685, 2024). "The analysis of gene expression levels of inflammatory mediators, including TNF-α and iNOS, indicators of pulmonary inflammation, in the different groups revealed the impact of CBZ on lung inflammation." (PMID 39441839, 2024). "TNF-α promotes both neutrophils and macrophages to accumulate in the pancreas, which leads to aggravate the local pancreatic inflammation and develop as a systemic inflammatory response." (PMID 36798729, 2023). "At the same time, a small amount of SCFAs produced by the colon reaches the systemic circulation to reduce the content of TNF-α in the blood, alleviate the blood inflammatory reaction, and indirectly alleviate liver inflammation." (PMID 37749663, 2023). "In contrast, TNF‐driven gut inflammation is fully rescued in germ‐free conditions, indicating that the microbiota is driving TNF‐induced gut inflammation." (PMID 37694693, 2023). "This study suggests that ETD and AHDs profoundly attenuate oxidized lipid-induced vascular inflammation and atherogenesis through oxidative-stress reduction and inhibition of TNF-α signaling." (PMID 37495992, 2023). "TNF-alpha is an important mediator of macrophage activation and granulomatous inflammation, and TNFi has been shown to be an effective treatment for patients with systemic and CS." (PMID 38077350, 2023). "Moreover, alirocumab not only affects lipid levels but may also offer additional cardiovascular benefits by reducing the activity of inflammatory cytokines (such as IL-18, IL-6, TNF-α) and other molecules associated with vascular inflammation (such as MMP-2, OPN, OPG)." (PMID 38017531, 2023). "The overexpression of TNF genes can lead to the development of pulmonary inflammation and fibrosis, and blocking TNF can dampen lung injury." (PMID 37118713, 2023). "Studies on animal models have also shown that brain inflammation is inhibited in animals that have received FA due to the reductions in the expression of pro-inflammatory cytokines IL-6, IL-1β, and TNF-α." (PMID 37590236, 2023). "Chronic inflammation, often referred to as inflammaging, is characterized by increased levels of pro-inflammatory markers such as IL-1, TNF, IFN, and IL-6 in geriatric patients." (PMID 37893234, 2023). "This association is plausible with the well‐established observation that proinflammatory cytokines such as TNF‐α induce endothelial cell activation and vascular inflammation." (PMID 36598149, 2023). "PSCs can be activated by pancreatic chronic inflammation, with cytokines and growth factors (e.g., IL-1β, IL-6, tumor necrosis factor alpha, or TNF-α, transforming growth factor beta 1, or TGF-β1) acting as stimulating molecules." (PMID 37296886, 2023). "During autoimmune inflammation, Arg1 is upregulated in monocyte-derived cells due to their interaction with TNF-α activated blood–brain barrier cells." (PMID 37893243, 2023). "Together, these data show that OTULIN also critically controls TNF-induced cell death in a transgenic model of chronic TNF-driven intestinal inflammation." (PMID 37598207, 2023). "PNFS at a concentration of 200 μg/mL downregulated the production of the inflammatory factors IL-1β and TNF-α to close to that of the control group in the UVB-induced inflammation model, indicating that PNFS can improve skin inflammation." (PMID 36903661, 2023). "Previous studies have shown that patients with chronic intestinal inflammation show elevated TNF-α level due to elevated numbers of TNF-α-secreting cells in the intestine." (PMID 36926182, 2023).
inflammation (continued). "Previous studies have found that, compared to females, male mice have increased neutrophil influx and TNFα production during LPS-induced airway inflammation using a higher dose of LPS (50 μg)." (PMID 37686333, 2023). "In our study, YCF treatment significantly inhibited pulmonary inflammation in silica-exposed rats, by reducing inflammatory cell infiltration, and decreasing the secretion of inflammatory chemokines, including TNF-α, IL-1β, and IL-6." (PMID 37381044, 2023). "All treatment choices were primarily based on literature and expert opinion, but csDMARDs and anti-TNFα were specifically considered for their efficacy in addressing both bone inflammation and skin/joint inflammation." (PMID 37480122, 2023). "Liver fat accumulation can promote the release of a variety of pro-inflammatory cytokines, such as tumor necrosis factor-α (TNF-α), interleukin-6 (IL-6), interleukin-1β (IL-1β), leading to liver inflammation and cellular damage." (PMID 35630624, 2022). "Current research shows that the combination of ellagic acid-hydroxyapatite combination is able to reduce the main proinflammatory cytokine of bone inflammation, TNF-α so that it can increase bone growth factors, BMP-4 and OPN, through IL-10." (PMID 36561943, 2022). "The aim of this study was to evaluate the molecular mechanisms of the in vitro protective effect of CCLE against TNF-α-induced acute intestinal inflammation on differentiated Caco-2 cells." (PMID 35222027, 2022). "Using a murine model of airway inflammation, we demonstrated enhancement of IL-17A/F, TNF-α, LCN-2 and neutrophil chemokine KC in the lungs, thus corroborating our findings in-vivo." (PMID 36517803, 2022). "In this study, the role of polygenic susceptibility on the pathway of chronic air pollution exposure to subclinical airway inflammation in elderly women was investigated focusing on three biomarkers TNF-α, LTB4, and the total number of cells in sputum." (PMID 36151579, 2022). "Proinflammatory cytokine TNF-α plays a key role in coordinating the inflammatory cascade of chronic intestinal inflammation." (PMID 35365737, 2022). "TNF-α and IL-6 are regarded as the major contributors to gastric inflammation and mucosal injury, and their serum levels are positively correlated with the severity of GU." (PMID 35140802, 2022). "It was reported that TNF-α is central to ACS induced lung inflammation in mice, while KC is a chemotactic factor for neutrophils, whose number has been shown to increase upon exposure to CS." (PMID 36009258, 2022). "Our study showed that IL-10 treatment significantly decreased TNF-α infiltration and the expression of IL-1β, IL-6, IL-8, and TNF-α in Ang II-induced vascular inflammation." (PMID 35528508, 2022). "Our previous study has shown that upregulation of HO-1 mediated through activation of JNK1/2 and p38 MAPK can protect against the TNFα-induced pulmonary inflammation." (PMID 35453467, 2022). "Studies have confirmed that the TNF-mediated NF-kappa B pathway can increase endothelial inflammation and significantly increase the degree of atherosclerotic lesions." (PMID 35845584, 2022). "Our results further highlight deleterious effects of TNF on epithelial cell homeostasis in a chronic model of intestinal inflammation." (PMID 35383266, 2022). "Our results showed that exosomes and miR-150 partially attenuated lung inflammation, including total cells, neutrophils, macrophages, TNF-α, IL-6, and IL-1β." (PMID 34750610, 2022). "During pulmonary inflammation, macrophages differentiate into M1 type and release pro-inflammatory factors (TNF-α, IL-6 and MCP-1)." (PMID 35266443, 2022). "We further studied the in-situ effect of the intestinal phase of the simulated digestion on an in vitro model of intestinal inflammation by using differentiated Caco-2 cells exposed to TNF-α." (PMID 36080136, 2022). "It has been reported that TNF signaling accelerates thrombosis and fibrosis in vivo, and TNFSF9 is implicated in lung inflammation and fibrosis." (PMID 34793333, 2022).
inflammation (continued). "The endothelialdysfunction in HFD-fed mice is associated with vascular inflammation.Therefore, we assessed the effect of γP-122-I on vascular inflammationand found that it reduced an HFD-triggered increase in the aorticexpression of TNF-α." (PMID 35133835, 2022). "Treatment with acetic acid resulted in severe histopathological destruction (necrosis, skin lesions, and inflammation) as well as an increase in the levels of the tongue tissue proinflammatory cytokines TNF-α and IL-2." (PMID 35161436, 2022). "In summary, these findings demonstrate the efficacy of combined pharmacological inhibition of IL-6 and TNF in suppression of Th17-mediated airway inflammation." (PMID 35408882, 2022). "The levels of TNF-α, IL-6, and IL-1β in the EtOH group were remarkably higher than that in the Ctrl group (p < 0.001), indicating the occurrence of liver inflammation." (PMID 35681289, 2022). "We thus also used VEGF-A-stimulated HUVECs as a second model of endothelial inflammation besides TNF-α stimulation." (PMID 36606274, 2022). "Persistent liver inflammation, immune-mediated liver damage, and upregulation release of proinflammatory cytokines TNF-α and IL-6 are present in NASH, chronic HBV, and HCV-induced HCC." (PMID 36189208, 2022). "If the presence of intestinal inflammation is confirmed, anti-IL-17 medication is contraindicated, with other therapeutic classes being preferred such as TNF inhibitors or corticosteroids." (PMID 35678656, 2022). "Under such conditions, monocytes, macrophages, IL-6, IL-1β, and TNF-α, which are involved in increasing oxidative stress and peripheral vascular inflammation, are likely to enhance subsequent progression of inflammation." (PMID 35370896, 2022). "We also confirmed the induction of selected proteins uniquely induced by the combination of IL-17A/F and TNF-α in a murine model of airway inflammation." (PMID 36517803, 2022). "RS provided also exerted a protective role against DSS-induced colonic inflammation as reflected by a decrease in colonic pro-inflammatory cytokine levels of IL-1β, IL-6, TNF-α, and IFN-γ in proximal or distal segments." (PMID 35836245, 2022). "Pro-inflammatory cytokines, TNF-α, and IL-1β, which are produced during intestinal inflammation have important intestinal epithelial tight junction barrier-modulating actions, highly related to inflammatory diseases of the gut." (PMID 35958130, 2022). "Abnormalities in the TNF signaling pathway was central to the persistence of chronic liver inflammation." (PMID 35721171, 2022). "We concluded that TLR2 regulates M. pneumoniae-mediated lung inflammation and TNF-α release through the TLR2-MyD88-NF-κB signaling pathway." (PMID 35372108, 2022). "Chronic intestinal inflammation is closely related to the expression of pro-inflammatory factors such as TNF-α, IL-1β, IL-6 and IL-8." (PMID 36185671, 2022). "The cytokine levels in bronchoalveolar lavage fluid (BALF) are usually measured to demonstrate the degree of lung inflammation, so TNF-α concentration was additionally measured there using ELISA." (PMID 35631731, 2022). "It is widely known that the transient expression of IL-1β can induce lung inflammation, increase TNF-α, and contribute to progressive tissue fibrosis." (PMID 35095920, 2021). "Previous reports have shown that 8-week anti-TNF-α therapy reduced aortic inflammation in RA patients." (PMID 34344436, 2021). "AS-IV improved endothelial function via the up-regulation of eNOS expression, alleviated oxidative stress via increasing antioxidant enzymes activities, and inhibited cardiac inflammation via down-regulating IL-6 and TNF-α expression." (PMID 34803698, 2021). "It is well known that the NF-κB pathway is crucial for the production of inflammatory cytokines, including IL-6 and TNF-α, both of which are important targets for the treatment of intestinal inflammation." (PMID 34322027, 2021).
inflammation (continued). "TNF-α and IL-6 are important mediators of the immune response and chronic inflammation, and the gene promoter regions of both cytokines contain the NF-κB binding site." (PMID 34712822, 2021). "PM2.5 exposure is also well documented to induce pulmonary inflammation, often characterized by the expression of several inflammatory markers, including tumor necrosis factor (TNF)-α, interleukin (IL)-1β, IL-6, and IL-10." (PMID 33419468, 2021). "LV gene expressions of pro-inflammatory cytokines, TNFα and IL-6, were significantly elevated in nicotine-administered rats compared to the vehicle controls (p < 0.05), indicative of cardiac inflammation." (PMID 34226619, 2021). "Studies have shown that lead exposure induces renal inflammation and increases the levels of interleukin-1β (IL-1β), tumor necrosis factor-α (TNF-α), and nitric oxide (NO) in the kidney tissue." (PMID 34578823, 2021). "They found a decreased level of copper after chronic tumor necrosis factor-alpha (TNF-alpha) dependent lung inflammation as well as in TNF-alpha overexpressing mice." (PMID 34836256, 2021). "SARS-CoV-2 can trigger endothelial inflammation and the production and release of inflammatory cytokines such as IL-1β, TNFα, and IL-6." (PMID 34792686, 2021). "In summary, our data demonstrate a novel role for Ataxin-10 in the regulation of TNF-α-induced endothelial inflammation via suppressing IRF-1." (PMID 34858081, 2021). "Studies have found that TNF-α increases the expression of epithelial myosin light chain kinase, leading to increased intestinal permeability in patients with intestinal inflammation." (PMID 34683415, 2021). "In animal models of acute pulmonary inflammation, LLLT relieved airway inflammation through the induction of IL−10 and reduction in the expression of macrophage inflammatory protein 2 and tumor necrosis factor (TNF)." (PMID 33671931, 2021). "Our results shown that PE effectively alleviate mammary inflammation by inhibiting the expression and secretion of IL-6, IL-1β, TNF-α in vivo and in vitro, and inhibiting the synthesis of iNOS and MPO." (PMID 34383710, 2021). "IL-6 induced the expression of acute-phase proteins during acute inflammation, and the levels of TNF-α and IL-6 in serum and colon tissue closely correlate with the severity of intestinal inflammation." (PMID 35010176, 2021). "Adherent-invasive E. coli are resistant to clearance by the immune system and induce an increased expression of the inflammatory cytokine tumor necrosis factor-α (TNF), which is fundamental for the onset and progression of gut inflammation." (PMID 34573354, 2021). "Mediators related to lung inflammation include tumor necrosis factor α (TNFα), interleukin-6 (IL-6), and interleukin-1β (IL-1β), which regulate maturation of dendritic cells and induce recruitment of neutrophils at inflammatory sites." (PMID 32752184, 2020). "For example, aerosolization of a lysate of nontypeable Haemophilus influenzae (NTHi) bacteria induced pulmonary inflammation characterized by increased concentrations of IL-6 and tumor necrosis factor (TNF)-α as well as increased neutrophils in BALF." (PMID 32471444, 2020). "Consumption of a low-fiber, high-fat, Western-style diet induces adiposity and adipose inflammation characterized by elevations in the M1:M2 macrophage ratio and pro-inflammatory TNF-α and IL-6 expression." (PMID 32092918, 2020). "TNF-α triggers the expression of cytokines and cell adhesion molecules for leukocytes’ recruitment during vascular inflammation." (PMID 31991780, 2020). "The marked reduction of pro-inflammatory cytokines in the serum appears to be emerging as an important target for the treatment of intestinal inflammation, such as TNF-α, IL-1β, and IFN-γ." (PMID 33208178, 2020). "Previous studies have shown that SiONPs exposure increases the production of TNF-α, IL-6, and IL-1β and elevates inflammatory cell recruitment into lung tissues, resulting in the aggravation of airway inflammation." (PMID 32164364, 2020).
inflammation (continued). "Previous studies demonstrated the elevated miR-155 expression in Kupffer cells after prolonged alcohol uptake, and that TNF served as a miR-155 target gene to give rise to liver inflammation." (PMID 32117757, 2020). "The gene expression of IL-1β, IL-6, and TNF-α in rat models of acute joint inflammation and in the cartilage of rat models of OA decreased significantly after LLLT (808 nm, 142 J/cm2) and laser irradiation (808 nm, 71 J/cm2), respectively." (PMID 32213810, 2020). "A reduction of IL-1β, TNF-α, and IL-6 and increased pulmonary inflammation was found when BCG was used to intravenously infect C57BL/6 diabetic mice." (PMID 32194998, 2020). "T. cruzi infection induced chronic heart inflammation, demonstrated by a significant increase in cell infiltration, fibrosis, and production of the proinflammatory cytokines TNF-α and IL-1β." (PMID 32393497, 2020). "Using human TNF-α transgenic mice, which develop spontaneous joint inflammation and cartilage destruction, IL-33 inhibited TNF-α-mediated bone loss via the IL-33/ST2 axis." (PMID 32046264, 2020). "We found that after unilateral DMV damage, the protective function of the vagus efferent nerve by Ach attenuated, esophageal inflammation aggravated, and the concentrations of the proinflammatory cytokines TNF-α, IL-6, and IL-1β significantly increased." (PMID 31281769, 2019). "Excessive production of inflammatory cytokines, such as TNF-α, which can amplify the inflammatory cascade by triggering the accumulation and activation of leukocytes, is often seen in intestinal inflammation." (PMID 31447849, 2019). "The LentiSigirr transduction effectively dampened the enhanced LPS-induced lung inflammation phenotype observed in Usp13−/− animals, with reduced cellular infiltration and neutrophils, TNF-α, and IL-1β." (PMID 31204278, 2019). "Our results show that PO suppresses lung inflammation by the reduction of IL-β, IL-6, TNF-α, PGE2, and TGF-β, as well as by the increase of IL-10 levels." (PMID 30609661, 2019). "Elevations of TNF-α and IL-1β—two well-known proinflammatory cytokines—can be verified both in acute and chronic airway inflammation." (PMID 31336570, 2019). "We conducted in vitro experiments using human umbilical vein endothelial cells (HUVECs) under stimulation with TNF-α as a model of vascular endothelial inflammation." (PMID 31452653, 2019). "It was reported that IL-18 expression in synovial tissue correlates with the severity of joint inflammation and the levels of pro-inflammatory cytokines tumor necrosis factor alpha (TNFα) and IL-1β." (PMID 31861496, 2019). "As a model of vascular endothelial inflammation, human umbilical vein endothelial cells (HUVECs) pretreated with aronia berry extract were stimulated with tumor necrosis factor-alpha (TNF-α)." (PMID 31452653, 2019). "These membrane TNF–carrying MVs are biologically more potent than soluble TNF in vivo, producing significant lung inflammation in mice." (PMID 30776316, 2019). "Our previous study has also shown that PDS exert more potent protective effects than PTS on TNF-α-induced vascular inflammation in human umbilical vein endothelial cells (HUVECs)." (PMID 31623159, 2019). "Pro-inflammatory cytokines such as IL-1α, IL-1β, IL-2, IL-5, IL-6, IFN-γ, MCP-1, MIP-1α, MIP-1β and TNF-α are shown to play an essential role in inducing age-related chronic inflammation." (PMID 31181695, 2019). "TNF-α and IL-1β are mostly produced by macrophages and infiltrated monocytes and involved in chronic hepatic inflammation and fibrosis." (PMID 30906791, 2019). "Proinflammatory cytokines, such as TNF-α, IL-6, which are released from activated microglia are considered to play important roles in the pathogenesis of neuro-inflammation in the CNS." (PMID 30400195, 2018). "IL-10, an anti-inflammatory cytokine, reportedly inhibits cigarette smoke-induced pulmonary neutrophilic inflammation and TNF-α expression in mice." (PMID 29650044, 2018).